LAG3 (lymphocyte activating 3)
Diseases named in the same sentence as LAG3 in open-access papers (continued):
Sharing a sentence is not in itself a finding about the gene and the disease.
tumor (continued). "Moreover, using ROC curve to determine the value of serum LAG-3 for predicting tumor response to TACE therapy, we chose >3723.1pg/ml as the cut-off point that combined maximal sensitivity with best specificity." (PMID 34691076, 2021). "Preclinical data indicated a strong anti-tumor efficacy of LAG-3 antagonists, esp." (PMID 33805268, 2021). "Furthermore, detailed mechanisms of anti-tumor immunotherapy, including blocking PD-1(L1), LAG-3, TIM-3, and TIGIT, are still unclear and require further research." (PMID 33717059, 2021). "Notably, along with PRMT5 deficiency in tumor cells, the expression of PD-1 and TIM-3 on CD8+ T cells was decreased and LAG-3 expression had a declined trend." (PMID 34522232, 2021). "Accordingly with these observations, the LAG-3 immune checkpoint has been identified as a potential target to improve productive tumor-specific T cell immunity, and various LAG-3 inhibitors have been developed and their efficacy evaluated both in preclinical models of MPM and in clinical trials." (PMID 34199722, 2021). "The interaction of LAG3 and FGL1 may cause changes in the tumor immune microenvironment, such as the reduction of IL-2 levels." (PMID 35111155, 2021). "LAG-3 single-domain antibody tumor uptake was also evaluated in mice bearing TC-1 or MO4 tumors." (PMID 33712537, 2021). "The same observation was made for LAG-3 expression on CD4+ T helper cells in the tumor." (PMID 33466653, 2021). "Blocking LAG3 can enhance tumor-infiltrating T cell response in patients with mismatch-repair proficient liver metastasis of CRC, which might be a newfound immunotherapy target for CRC liver metastasis." (PMID 34326840, 2021). "The combined analysis of PD-1/LAG-3 expression within the stromal tumor compartment and immune phenotype further improved DFS discrimination: “hot” but PD-1− PBTs displayed a significantly better DFS, while “hot” but PD-1+ PBTs showed the same reduced DFS as “cold” PD-1+ or PD-1− tumors." (PMID 33413541, 2021). "We next assessed whether the pretreatment serum LAG-3 and PD-L1 levels could predict tumor response to TACE therapy in HCC." (PMID 34691076, 2021). "Peptide and DNA vaccines that double block PD-1 and LAG3 showed a great anti-tumor effect, especially in a MycCaP prostate cancer model, which significantly increased the levels of CD8+T cells, which express more immune checkpoints, underlying the role of APCs." (PMID 35111155, 2021). "Furthermore, LAG-3 expression has been noted in tumor-infiltrating T cells in tumor specimens from PDAC patients." (PMID 34356465, 2021). "Thus, although LAG3 is primarily expressed on lymphocytes it is also found in NSCLC tumor cell lines and its expression is regulated by various factors." (PMID 35111155, 2021). "Moreover, previous studies show that the presence of LAG3+ intraepithelial tumor infiltrating lymphocytes (iTILs) is significantly related to younger age, large tumor size, ER/PR-negativity, and a high Ki67 proliferation index." (PMID 34267742, 2021). "To further probe the therapeutic potential of the combination of anti-LAG3 and PI3Kδ inhibition, we commenced both treatments in established tumours and found that combination therapy was able to reduce tumour burden, with some animals able to eradicate established tumours." (PMID 33824480, 2021). "Persistent tumour antigen presentation induces chronic LAG3 expression on T-cells within the TME, leading to the impairment of CD8+ T-cell function through a progressive loss of cytokine production and cancer cell killing ability, a phenomenon dubbed T-cell functional ‘exhaustion’." (PMID 34944851, 2021). "We found that CD274 and CTLA4 show significantly higher expression in the TNFSF10high group than in the TNFSF10low group; however, PD-L1 (CD274) was predominantly expressed by tumors while CTLA4 and LAG3 were mostly expressed by T cells in the tumor microenvironment." (PMID 34167551, 2021).
tumor (continued). "Furthermore, co-expression of LAG-3 and PD-1 on TILs has been observed in several mouse tumour models." (PMID 33995362, 2021). "Additionally, B7-H3+ tumor samples exhibited higher PD-1+ and LAG-3+ cell densities than B7-H3− tumor samples." (PMID 34081621, 2021). "Many studies have reported the predictive role of LAG3 in tumor prognosis." (PMID 35111155, 2021). "Dual inhibition of LAG-3 and other ICIs synergistically increases T cell tumour anti-activities." (PMID 33921181, 2021). "In an independent series of 166 patients treated with standard ABVD regimen, IHC confirmed that expression of LAG3+ T cells correlated with the loss of CMH-class II by tumor cells, with no impact on prognosis." (PMID 33732232, 2021). "In the mouse AB1-HA BALB/cJ mesothelioma model, compared to the control group, blocking both PD-L1 (durvalumab) and LAG3 effectively inhibited tumor growth and could be beneficial for mouse survival." (PMID 35111155, 2021). "Notably, the combination therapy of anti-PD-1 mAb or anti-PD-L1 mAb plus anti-Tim-3 mAb plus/or anti-Lag-3 mAb showed remarkably additive effect in the cytotoxicity of the tumor antigen specific CTL clones against GC cells as compared to ICI monotherapy." (PMID 33611641, 2021). "LAG-3 signaling is coopted in the tumor microenvironment (TME) to enable tumor cell escape." (PMID 33712537, 2021). "Indeed, we found that Tox and Tox2 directly control the transcriptional regulation of Pdcd1 and Lag3 expression, largely determining the functional incompetence of tumor-infiltrating CD4+ T cells from CD4/ALK4-KO mice." (PMID 34548096, 2021). "LAG3 was associated with AJCC stage, ER, PR, and HER2 status in both datasets, and was associated with T stage in TGCA data, as well as age, tumor size, and tumor grade in the METABRIC cohort." (PMID 34267742, 2021). "At the same time, there were more CD8+ T cells highly infiltrated, more active function of inflammation-promoting, higher immune score, and higher activity of TIM3, LAG3, and PD-L1 in cluster 2, which could be identified as the hot tumor definitely." (PMID 34790235, 2021). "LAG3 is the third alternative inhibitory receptor targeted in the tumor microenvironment." (PMID 34220795, 2021). "Moreover, it is generally accepted that the high expression of immune checkpoints such as CTLA4, PD-1, BTLA, CD274, and LAG3 will benefit tumor cells to escape immune surveillance, avoid immune-mediated apoptosis, and finally lead to poor prognosis." (PMID 34745259, 2021). "A higher CNV burden and attenuated anti-tumor immune activity, reflected by lower cytolytic activity scores, fewer neoantigens, and mRNA-level downregulation of immunomodulators such as HAVCR2 and LAG3, have been linked to early-onset OTSCC." (PMID 33923093, 2021). "Recently, several alternative immune checkpoints in the tumour microenvironment have been targeted to develop new inhibitors or therapeutic agents (under clinical trial) such as anti-LAG-3 antibody and TIM-3 in an attempt to improve the efficacy of immunotherapy." (PMID 34968365, 2021). "Generally speaking, high levels of LAG-3 were positively correlated with large tumor burden and immune tolerance, which may contribute to less effective of TACE." (PMID 34691076, 2021). "In addition, immune checkpoints including PD-L1, HAVCR2, TIGIT, and LAG3 in the high-risk group were also higher than those in the low-risk group, which indicated that patients in the high-risk group might belong to the “hot” tumor that was tended to benefit from immune checkpoint inhibitor therapy." (PMID 35027921, 2021). "The role of LAG3 in tumor immune can be modulated by methylation." (PMID 35111155, 2021). "Many factors such as immune contexture and tumor microenvironment, expression of PD-L1 and LAG3, TMB, genetic and epigenetic alterations, antigen-presenting molecules (MHC, HLA) and microbiota may all contribute to the resistance to immunotherapy." (PMID 34926258, 2021).
tumor (continued). "Since LAG-3 is often co-expressed with PD-1 on tumor-infiltrating lymphocytes, it has been proposed that blockade of LAG-3 in conjunction with blockade of PD-1 could be promising to increase treatment response." (PMID 34727262, 2021). "KIF18B, PD-L1, and Lag-3 showed the same expression trends in tumors, suggesting that they may share some pathways that promote tumor aggressiveness." (PMID 34109209, 2021). "Synergy between LAG-3 and PD1s has been reported in tumor models, suggesting that dual immunotherapeutic inhibition would enhance efficacy and may extend to multiple tumor types." (PMID 35008245, 2021). "Tumor-infiltrating CD4+ T cells upregulated PD-1, cytotoxic T-lymphocyte-associated protein-4 (CTLA-4), T cell immunoglobulin and mucin domain-3 (TIM-3) and LAG-3." (PMID 34660608, 2021). "We therefore tested whether IL‐12 treatment affected the expression of the checkpoint molecules PD‐1 and LAG3 on patient‐derived anti‐tumor T cells in the X‐mouse model." (PMID 33552509, 2021). "LAG3 may play an important role in regulating the tumor immune microenvironment of T cells and other immune cells." (PMID 34267742, 2021). "Notably, LAG-3 and PD-1 are co-expressed at high levels in tumor infiltrating lymphocytes in certain tumor model mice and the inhibition of both molecules enhances CD8+ effector T cell numbers." (PMID 34356465, 2021). "Paradoxically, T cell PD-1 and Lag3 expression were reduced in tumor-bearing KI mice." (PMID 33462142, 2021). "In order to investigate on the effects of anti-PD-L1 or anti-LAG-3 mAbs on HuT-78 in the presence of lymphocytes, we co-cultured tumor cells with hPBMCs (Effector:Target cells ratio 5:1) for 48 h and treated them with atezolizumab, PD-L1_1, LAG-3_1, or their combinations." (PMID 35008285, 2021). "Therefore, the blockade of LAG-3 helps to restore the immune activity of T cells and, consequently, their anti-tumor activity." (PMID 34371708, 2021). "Rather, one may assume that the presence of LAG-3 results in increased inhibition of both T cell activation and proliferation and thus contributes to an immune-suppressive tumor microenvironment facilitating tumor growth and metastasis." (PMID 34442393, 2021). "A recent study demonstrated that agents targeting the FGL1/LAG-3 pathway could stimulate tumor immunity and inhibit tumor growth." (PMID 33633363, 2021). "In contrast, LAG-3 monoclonal antibody can restore the body’s anti-tumor immune activity by reducing the number of bone marrow-derived suppressor cells (MDSC), inhibiting the activity of Treg cells in the tumor microenvironment and increasing the number of activated CD8+ T cells." (PMID 34869005, 2021). "Furthermore, ligands Galectin-3 and HLA class II were increased in monosomy 3 tumours and the expression of LAG3 correlated with the presence of an inflammatory phenotype (T cell fraction, macrophages, HLA-A and HLA-B expression: all p < 0.001)." (PMID 34503258, 2021). "Indeed like TIM-3, LAG-3 can be co-expressed with other ICIs like PD1 as observed in preclinical mouse tumour models and cancer patients with intratumoral T-cell dysfunction that accentuates immune escape and increased tumour growth." (PMID 33921181, 2021). "By contrast, a recent report showed that chronic stimulation of adaptive NK cells from HCMV seropositive donors via NKG2C and IL-15, NKp30, or NKG2D increased PD-1 and LAG-3 surface expression, downregulating NK activity during subsequent interactions with tumor targets." (PMID 32153582, 2020). "LAG-3 is known to promote tumor escape through an induction of immunosuppression." (PMID 33374804, 2020). "To target these cells, as well as LAG3+ CD8+ T cells, we determined whether LAG3-blocking antibodies would improve control of tumor growth." (PMID 33093155, 2020).
tumor (continued). "The expression of LAG-3 in the TME has been observed on TILs, in particular CD4+ and CD8+ T cells, including regulatory T cells (Tregs); NKT cells; B cells; NK cells as well as on plasmacytoid dendritic cells (pDCs) and tumor-associated macrophages (TAMs)." (PMID 33374804, 2020). "Importantly, the DPTs at the tumor sites expressed higher levels of PD-1, LAG-3, and TIM-3 than the CD4+ T cells, CD8+ T cells, Tregs, and naïve T cells." (PMID 32457755, 2020). "We found that PD-1, LAG-3 and Tim-3 were the three most upregulated checkpoint receptors on non-Treg CD4+ and CD8+ TILs as compared to autologous peripheral T cells, whereas PD-1, CTLA-4 and LAG-3 were dominant on tumor-associated Tregs." (PMID 32582215, 2020). "Finally, to address the potential utility of PI3Kδ inhibition in therapeutic setting, we commenced PI-3065 treatment once tumors became palpable (day 7 post-tumor inoculation) either alone or in combination with anti-LAG3." (PMID 33093155, 2020). "Importantly, antibodies against PD-L1, TIM-3, or LAG-3 restore responses of HCC-derived T cells to tumor antigens, and treatment with combinations of these antibodies demonstrate additive effects in the restoration of T-cell function response to TAA." (PMID 32443599, 2020). "However, further functional investigations with regard to LAG3 expression and interactions with tumour cells are necessary." (PMID 32592066, 2020). "However, more research is required to confirm if a tumor-specific prognostic value of LAG-3 really exists." (PMID 33374804, 2020). "LAG3 and PD-1 are commonly described as markers of exhausted T cells with combination targeting of the two being effective in eliciting a strong T cell response leading to tumor clearance." (PMID 33247183, 2020). "Even though the two cohorts revealed divergent frequencies for some tumor types, the prevalence of LAG3-expressing TILs in SDC, one of the most aggressive entities, was consistently high (50% and 66.7% for the test cohort and the validation cohort, respectively)." (PMID 32232506, 2020). "Furthermore, LAG‐3 not only is expressed in tumor‐infiltrating lymphocytes in NSCLC patients but also is ectopically expressed in tumor cells and associated with TNM stage." (PMID 32077528, 2020). "LAG-3 and PD-1 have shown synergism in T-cell functional regulation to promote tumor immune escape." (PMID 32117298, 2020). "For bead 14, that targets a CpG site located within the gene body and bead 15 probing a CpG within the CTCF binding site, an inverse correlation between LAG3 methylation and tumor cell content/purity of the tumor tissue could be shown." (PMID 32861198, 2020). "Importantly, anti-tumor immunity was enhanced by treatment with a combination of anti-PD-1 and LAG3 ICI." (PMID 33162991, 2020). "However, LAG-3 is also expressed on PD-1+ tumor-infiltrating effectors cells (TILs) found in both pre-clinical models and patients, where they promote tumor escape." (PMID 32610578, 2020). "In addition, LAG-3 synergizes with PD-1 in T-cell functional regulation to promote tumor immune escape." (PMID 33255582, 2020). "Future work investigating the effect of VISTA and PD-1 combination blockade on other co-inhibitory receptors (TIM-3, LAG-3, TIGIT) and inhibitory cell types (regulatory T cells, tumor associated macrophages) will be necessary to more comprehensively define the therapy’s mechanism of action." (PMID 32938950, 2020). "Thus, in the case of endoscopically taken biopsies LAG3 expression in EAC can serve as a reliable predictor regarding the overall LAG3 expression within the tumour." (PMID 32592066, 2020). "Besides PD-1, targeted in our ICPI therapy, we have observed generalized Tim3 and Lag3 expression on tumor-specific lymphocytes, as already reported in HCC patients." (PMID 33207844, 2020). "LAG3 immunostaining was localised in the cytoplasm/membrane of tumour infiltrating lymphocytes." (PMID 32592066, 2020).
tumor (continued). "PD-1, TIM-3 and LAG-3 inhibitors are able to enhance the T-cell response to tumor antigens." (PMID 31960110, 2020). "LAG3 expression is induced upon immune cell infiltration in tumor tissue." (PMID 32861198, 2020). "First, inhibitory signaling via LAG‐3 is transmitted by its cytoplasmic KIEELE domain when the receptor binds with high affinity to MHC class II,161 highlighting the potential for both tumor‐associated APC and MHC class II‐expressing cancer cells to suppress T cell function via this pathway." (PMID 32508018, 2020). "Besides this, tumor-infiltrating Treg cells also express high levels of various inhibitory molecules such as LAG3, TIM3 and GITR that confer a strong immunosuppressive activity on effector cells." (PMID 32636725, 2020). "Consequently, the presence of LAG-3 on tumor-infiltrating immune cells has been described to be associated with poor prognosis and tumor progression." (PMID 33374804, 2020). "Indeed, LAG-3 was co-expressed with PD-1 on Tregs and CD8+ T cells; however, strikingly, LAG-3 expression was also observed on tumor-associated macrophages and a proportion of malignant B cells." (PMID 32787882, 2020). "The role of LAG3 in cancer immunology has been implicated in negative regulation of T cell responses and – together with PD-1 – in T cell exhaustion, facilitating tumor escape." (PMID 32861198, 2020). "Therefore, to further strengthen JX-based immunotherapy, we treated peritoneal MC38 tumor-bearing mice with anti-PD-L1 or anti-LAG-3." (PMID 33199510, 2020). "High expression of LAG3 is correlated with T cell dysfunction in tumor environment." (PMID 33457419, 2020). "Moreover, LAG3 expression in conjunction with PD-L1 expression has been demonstrated on tumor infiltrating CD4+ and CD8+ T cells and during the course of tumor cell - immune cell interaction." (PMID 32861198, 2020). "A preclinical study by Burova and colleagues showed that REGN3767, a fully human antibody targeting LAG3, increased the efficacy of PD-1 blockade in a humanized mouse model and enhanced the production of pro-inflammatory cytokines by tumor-specific T lymphocytes." (PMID 33327433, 2020). "However, when combination treatment with PI-3065 and anti-LAG3, as observed earlier, enhanced control of tumor growth, with clearance of tumors in some animals." (PMID 33093155, 2020). "However, other immune-suppressive checkpoint genes—including lymphocyte-activation gene 3 (LAG-3) and CTLA-4—and immunosuppressive components—such as T-reg, tumor-associated alveolar macrophages, and tumor-associated neutrophils—were unchanged." (PMID 32380703, 2020). "Accordingly, we found differences in the methylation status of LAG3 depending on the tumor site." (PMID 32861198, 2020). "The upregulated expression of PD-1 and LAG3 may lead to immune suppressive effect in the TME, causing its failure to shrink the tumor." (PMID 32719347, 2020). "CAR-T therapy enhances the expression of LAG-3 in CAR-T cells in the tumor microenvironment." (PMID 33167514, 2020). "While monotherapy with anti-PD-L1 or anti-LAG-3 showed only marginal efficacies, the combined therapy of JX to anti-PD-L1 or anti-LAG-3 revealed stronger anti-tumor efficacies and further suppressed the formation of malignant ascites within the peritoneal cavity compared with monotherapies." (PMID 33199510, 2020). "In addition to the clinical efficacy of dual PD-1 and LAG-3 blockade, functional impacts of myeloid LAG-3 and tumor-intrinsic LAG-3 will require further investigation." (PMID 32787882, 2020). "However, reports on the prognostic value of LAG3 expression are controversial, depending on the specific tumor entity." (PMID 32861198, 2020). "However, when anti-LAG3 blocking antibody was used in combination with PI-3065 this resulted in a significantly greater tumor control than either PI-3065 or anti-LAG3 treatment alone." (PMID 33093155, 2020).